INS (insulin)
Diseases named in the same sentence as INS in open-access papers (continued):
Sharing a sentence is not in itself a finding about the gene and the disease.
tumor (continued). "The different distribution of proliferative cells in the racemose larvae and their sensitivity to insulin may reflect significant changes at the cellular and molecular levels involved in their tumor-like growth." (PMID 33750965, 2021). "We also carried out tumor spheroid formation assays following insulin treatment." (PMID 33495474, 2021). "Importantly, 6mGHRKO males have enhanced insulin sensitivity and reduced neoplasms while females exhibited increased median and maximal lifespan." (PMID 34811874, 2021). "The indirect insulin-dependent mechanism is based on insulin’s growth-promoting effect on tumor cells, and the direct insulin-independent mechanism may occur both through AMPK dependently or independently through Rag-GTPase responses to energy status." (PMID 34436421, 2021). "Insulin was found to stimulate insulin–IGF-1 signaling in tumor cells and result in an activation of the oncogenic Ras–MAPK and PI3K–Akt pathways (MAPK = mitogen-activated protein kinase, PI3K = phosphoinositide 3-kinase), which subsequently stimulate tumor cell growth." (PMID 33803268, 2021). "The relative order of high to low expression samples did not change substantially, but with the more sensitive method, we detected the expression of insulin in two additional samples, samples 6 and 11, giving detectable expression of INS transcript in 19 of 20 tumours." (PMID 34170845, 2021). "72% of PCa patients expressed activated insulin/IGF receptors on tumor cells." (PMID 34439378, 2021). "Moreover, tumor cells can produce hybrid forms of insulin and IGF-1 receptors that can either be activated by insulin, IGF-1, and/or IGF-2." (PMID 33920079, 2021). "Nineteen tumours expressed high levels of INS and INS-IGF2 transcripts." (PMID 34170845, 2021). "Thus, we concluded that amelioration of the prediabetic condition, at least in terms of blood glucose and insulin levels, by a high dose of AdipoRon was unable to suppress orthotopic tumour growth of the cells in the present experimental setting." (PMID 33536560, 2021). "Therefore, prospective clinical studies are needed to evaluate the possible tumor growth-promoting effects of these insulin analogues." (PMID 34535145, 2021). "The reason seems to be that insulin and glucagon co-expressing cells may contain cells under neoplasia, dedifferentiation and transdifferentiation into any type of islet cells." (PMID 34493754, 2021). "However, despite impairments in insulin-stimulated glucose uptake in tumor-bearing mice, signaling via Akt and TBC1D4 was, surprisingly, elevated." (PMID 33801684, 2021). "The most important mechanism is that it can reduce the expression of potential growth factors such as insulin and IGF-1, which can stimulate the survival and mitosis of tumor cells, and then inhibit the insulin-dependent mechanisms in the process of growth stimulation and metabolism." (PMID 34675807, 2021). "Furthermore, InsR expression was visible in the cytoplasm of tumor cells indicating InsR activation by the insulin/IGF axis." (PMID 34202040, 2021). "IGFBP7, similar to IGFBP3, might have a dual role as a tumor suppressor within the IGF/insulin system while simultaneously having tumor-promoting effects through other pathways." (PMID 34606580, 2021). "In our study, we find that SIRT6 over‐expression could restore insulin secretion to normal levels in tumour‐bearing mice." (PMID 34212132, 2021). "For example, FF has been shown to inhibit tumor cell proliferation and diapedesis, angiogenesis, endothelin‐1 expression by endothelial cells, renal organ cation transporter, and insulin secretion, which are reportedly mediated independently of PPAR‐α." (PMID 34228906, 2021). "However, in tumour‐bearing mice, plasma insulin levels were significantly higher in Tu‐Sk.T6Tg mice, compared with Tu‐CN animals." (PMID 34212132, 2021). "Tumoral cells secrete an antagonist that attenuates insulin signaling in neurons." (PMID 33526430, 2021).
tumor (continued). "Interestingly, earlier studies had revealed other tumor-derived secreted factors that are required for cachexia and, like Ilp8, ultimately converge on systemic insulin signaling." (PMID 34831432, 2021). "Staining with anti-insulin antibodies was mostly at a low level (score 1, twelve tumours)." (PMID 34170845, 2021). "The anti-insulin staining strongly suggests that insulin is produced by these tumours." (PMID 34170845, 2021). "Overall, these findings suggest that the tumor itself negatively impacts on cardiac function through secreted factors that act in an endocrine manner and identify dysregulation of the cardiac insulin pathway as a major mechanism whereby the tumor negatively affects cardiac cell survival." (PMID 33547494, 2021). "These dietary approaches can reduce nutrient levels/factors that promote proliferation, particularly glucose, IGF1 and insulin, increase ketones body level which help to slow tumor growth and promote antitumor immunity and sensitization of cancer cells to the action of the immune system." (PMID 34322508, 2021). "In addition to defective insulin signaling, the massive glucose uptake by the tumor can deprive cardiac cells of a pivotal energetic source during stress conditions." (PMID 33547494, 2021). "Plasma insulin levels or an additional low carbohydrate diet could lend insight into the role of insulin and insulin resistance in tumor formation and metastasis in HFD models." (PMID 34371939, 2021). "Aspirin alleviated tumor growth in obese mice, paralleled by a decrease in systemic glucose, insulin, inflammation, platelet activation, and glutamine, along with the tumor expression of cell proliferation, aerobic glycolysis, glutaminolysis, platelets, and leukocyte molecules." (PMID 32121098, 2020). "As nutrient levels of BCAAs, substrates of BCATc, regulate the PI3K/Akt pathway we hypothesized that increased expression of BCATc would contribute to tumour cell growth through upregulation of the insulin/IGF-1 signalling pathway." (PMID 32523652, 2020). "Vegetables and fruits intake may modify tumor metabolism through a reduction of the inflammation, a moderate caloric restriction, and inducing changes in patient’s insulin levels and gut microbiome." (PMID 32764484, 2020). "Additionally, mice fed a low-fat diet show significantly lower levels of serum prostate-specific antigen (PSA), serum insulin, and tumor Igf1 mRNA levels relative to HFD mice, as well as a slower tumor-growth rate in LAPC4 xenografts." (PMID 32093338, 2020). "Subgroup analysis according to the types of hypoglycemic agents including GLP-1RA, DPP-4i, SGLT2i, and insulin showed that none of these hypoglycemic agents were associated with decreased incidence of neoplasm in weight reduction group." (PMID 33424764, 2020). "Adiponectin, which has been shown to play an anti-tumour role due to its anti-inflammatory and antiproliferative effects and antagonism to insulin resistance leading to the inhibition of tumour growth and angiogenesis, is mainly secreted by white adipose tissue." (PMID 33008076, 2020). "This indicates that these dysregulated miRNAs and their target genes may be involving in the tumorigenesis, drug resistance and tumor progression of the insulin resistant HCC cell line." (PMID 32210717, 2020). "In addition, insulin also activates the Akt signaling pathway to conservatively execute the insulin metabolic response in tumor cells, driving the metabolism of tumor cells." (PMID 33250766, 2020). "The p16INK4a encoded by CDKN2A is a tumor suppressor and inhibits CDK4 (cyclin-dependent kinase) influencing pancreatic β cell proliferation, through decreased cell mass and subsequent decreased insulin release." (PMID 33017871, 2020).
tumor (continued). "The mostly lobular pattern, Case 6 consisted of large oncocytic cells, which were strongly and diffusely stained for insulin but patchy and linear stained for CgA at 1% of tumor cell cytoplasm adjacent to the cell membrane and strongly and diffusely immunostained for SPY." (PMID 32020844, 2020). "No statistical association was found between the tumor size and preoperative glucose, C-peptide and insulin levels." (PMID 32394681, 2020). "In addition to insulin-sensitizing, lipid metabolism, and anti-inflammatory properties, recent studies have revealed that adiponectin possesses potent tumor growth-limiting effects through multiple mechanisms." (PMID 32155890, 2020). "They assessed circulating interleukin-6 (IL-6), VEGF, fasting insulin, and tumor expression of insulin-like growth factor-1 receptor (IGF-1R), insulin receptor (IR), insulin-like growth factor-1 (IGF-1), and RAGE markers before surgery and 6 months after tumor surgery." (PMID 33117687, 2020). "Rising glucose levels without a high insulin state were associated with the tumor’s acquisition of varying degrees of invasive and proliferative character in hormone receptor positive and TNBC cell lines." (PMID 32230859, 2020). "In addition, metformin indirectly exerts an anti-tumor effect via reducing serum insulin level, repressing the signaling pathway of insulin and insulin-like growth factor 1 (I/IGF-1)/phosphoinositide 3-kinase (PI3K)/Akt/mTOR or I/IGF-1/Ras/Raf/MEK/ERK." (PMID 33382703, 2020). "In this case, our patient’s initial subtle symptoms, which manifested 8 years prior to presentation, could likely correspond to the developing insulin-secreting tumor." (PMID 32605595, 2020). "In addition, previous studies and our results revealed that insulin and CDKs were the targets of Sorafenib that inhibited tumor growth." (PMID 33344655, 2020). "The antiplatelet drug aspirin, mitigated tumor growth in obese mice, paralleled by a decrease in systemic glucose, insulin, inflammation, platelet activation, glutamine and tumor expression of cell proliferation, aerobic glycolysis, glutaminolysis, platelets, and leukocyte molecules." (PMID 32121098, 2020). "The molecular mechanisms which lead to an increased risk of EC in PCOS probably arise as a result of complex interactions between a range of systems and pathways, including chronic unopposed oestrogen, the insulin and the lipid pathways and tumour regulatory genes." (PMID 32635401, 2020). "However, IGF-1R and RAGE expressions were increased in tumor tissues; also, fasting insulin levels in CRC patients with metabolic syndrome were significantly enhanced." (PMID 33117687, 2020). "Our metabolic studies in BP-3 treated tumor-bearing mice, where BP-3 exposure is long term, suggest modestly increased insulin levels that could plausibly enhance proliferation." (PMID 33400736, 2020). "One interesting example is the lack of any association between tumor size, plasma C-peptide, and insulin levels." (PMID 32394681, 2020). "High levels of insulin and insulin-like growth factors (IGFs) may also play direct role in stimulating tumor proliferation in obese women, independently from sexual hormone pathways." (PMID 33109233, 2020). "Therefore, the study of the new pharmacologic agent such as metformin, that modulates insulin sensitivity and probably inhibits tumor cell growth, is become interesting as a role in the adjuvant treatment of EC patients." (PMID 32212801, 2020). "KMT reduces circulating levels of glucose and insulin that are needed for rapid tumor growth." (PMID 32219096, 2020). "Elevated glucose and insulin levels may increase CRC risk through their pro‐proliferation, pro‐angiogenesis, and apoptosis inhabitation effects against tumor cell." (PMID 32400092, 2020). "As such, enhancing insulin sensitivity can lead to tumor growth inhibition and cell cycle arrest." (PMID 33108409, 2020).
tumor (continued). "Moreover, we found a positive correlation between preoperative S-insulin levels and the glutathione content in tumor tissue (r = 0.680; p = 0.002)." (PMID 31801490, 2019). "Finally, as an insulin feedback was reported to limit the efficacy of PI3K inhibition in several tumor models, we checked for the effects of the combined PIK‐75 plus vemurafenib therapy on the expression of the IRS‐1." (PMID 31115969, 2019). "However, infusion of insulin via subcutaneous pellet to match plasma insulin concentrations in CRMP-treated mice to those of HFD control animals completely abrogated the effect of CRMP to slow tumor growth." (PMID 31867105, 2019). "In mice with normal levels of glucose and insulin, combined metformin and cisplatin treatment decreased the tumor volume to a significantly greater extent than cisplatin treatment alone, suggesting that metformin has potential as a therapeutic agent against TNBC in combination with cisplatin." (PMID 31640742, 2019). "Insulin signaling is one of the important pathways involved in tumor initiation and progression; therefore, we proposed that the anti-metastatic effect of curcumin may mediate the downregulation of insulin and insulin-like growth factor-1 receptors." (PMID 30987250, 2019). "It is well documented that insulin supports tumor cell proliferation." (PMID 31212761, 2019). "Elevated concentrations of insulin are believed to activate the insulin-like growth factor pathway which, in turn, stimulates the growth and proliferation of cells and inhibits apoptosis, subsequently leading to tumor development." (PMID 30670692, 2019). "Myokines may also influence the onset and the course of other diseases through their endocrine functions, as they interplay with body weight regulation, inflammation, insulin sensitivity, tumor growth, and cognitive function." (PMID 31849710, 2019). "In contrast, insulin—at doses that are supraphysiologic but commonly used in in vitro studies in the literature—promoted both glucose uptake and oxidation in E0771 tumors, accelerating tumor cell division." (PMID 31867105, 2019). "Pancreatic islet hyperplasia and co‐secretion of insulin (in addition to somatostatin) from tumour cells, respectively, have been characterized as completely distinct mechanisms of hypoglycaemia at both the functional and morphological levels in these two patients." (PMID 31592116, 2019). "Interestingly, tumor-bearing mice showed substantially decreased plasma levels of amylin, which is co-secreted with insulin by pancreatic β–cells." (PMID 31752313, 2019). "Secondly, it may indirectly influence cancer biology by modulating insulin sensitivity, inflammation and tumor angiogenesis." (PMID 31212761, 2019). "Importantly, SIRT4 can regulate insulin secretion and has tumour suppressor activity via modulation of glutamate dehydrogenase." (PMID 31744516, 2019). "Thus, the results indicate that insulin combined with FU significantly inhibited tumor growth when compared to FU or insulin alone." (PMID 31719636, 2019). "At the molecular level, several mechanisms of action linked to multiple pathways critical to tumor growth have been proposed for MET anticancer effects and have been broadly classified into indirect or insulin-dependent pathways and direct or insulin-independent pathways." (PMID 30918522, 2019). "In addition, TrxR1 activity in HUH-7 cells and tumor xenografts was measured by an endpoint insulin reduction assay, which showed that treatment with PL significantly reduced the activity of TrxR1." (PMID 31680962, 2019). "Moreover, KD regulates insulin and tumor related growth factors (like insulin growth factor-1, IGF-1)." (PMID 31398922, 2019). "In fact, the leucine-rich diet clearly demonstrated that could ensure maintenance of serum insulin levels throughout the course of tumour development, improving the muscle protein synthesis." (PMID 30975087, 2019).
tumor (continued). "Moreover, the potential role of insulin-secreting endocrine cells in the progression of PDAC and the impact of PDAC tumor microenvironment on insulin-secreting endocrine cells is yet to be discovered." (PMID 29475434, 2018). "Further, limited information is available regarding the question whether insulin analogs are also capable of regulating the key processes of tumor cell motility, invasion, and metastasis." (PMID 29615978, 2018). "Finally, in the atypical teratoid/rhabdoid tumor, a highly aggressive pediatric cancer of the central nervous system, a peculiar autocrine signaling involving insulin and the IR was discovered, modulating the tumor growth." (PMID 30453495, 2018). "Therefore, we examined the influence of daily repeated treatment with NYT on the insulin signaling molecular pathway in the skeletal muscle of tumor-bearing mice." (PMID 30555329, 2018). "Training and tumor cell inoculation showed distinct effects on total insulin content." (PMID 29867528, 2018). "We also included how PTEN and PTEN regulated metabolic functions may act paradoxically toward insulin sensitivity and tumor metabolism and growth." (PMID 30038596, 2018). "Considering that tumor cells demonstrate abnormal glucose uptake to survive and proliferate and that insulin is a growth factor that can induce tumor cell proliferation, these factors likely influence tumor growth and metastasis in Walker 256 tumor-bearing adult (90 days old) rats." (PMID 29867528, 2018). "In addition, scrib mutant RasV12-expressing tumours secrete the insulin growth factor binding protein, ImpL2, which is an antagonist of Insulin signalling that results in wasting of adipose, muscle, and gonadal tissues in the larvae." (PMID 29693007, 2018). "Insulin might also stimulate tumor promotion via other receptors such as the estrogen receptor (ER) pathway." (PMID 29486734, 2018). "Actually, hepatocytes may acquire the capacity to adapt insulin-dependent mechanisms for their proliferation and survival during chronic liver injury, and sequentially may promote premalignant transformation and tumor growth." (PMID 30477453, 2018). "There is experimental support that insulin interacts with estrogens and might stimulate tumor growth via the ER pathway." (PMID 29486734, 2018). "This hypothesis was tested by searching in insulin-challenged MCF-10A cells features suggestive of a tumor-like phenotype." (PMID 30138330, 2018). "Differences in levels of BMI-related and reproductive hormones, i.e., factors related to menopausal status, such as insulin, estrogen and adipokine, may play a role in tumor subtype formation." (PMID 28076434, 2017). "The aim of the present study was to investigate in vivo, whether the benefit of insulin treatment overrides its tumor proliferating effect." (PMID 28903776, 2017). "This provides evidence that, although sugar might promote insulin resistance, it will also enhance tumor formation in an insulin/PI3K-dependent manner." (PMID 28580187, 2017). "Therefore, IGF1 and insulin more likely (at lower concentrations) enhance tumour cell survival than proliferation, via activation and maintenance of phosphatidylinositol 3-kinase activity and p-Akt/PKB." (PMID 28316059, 2017). "These actions have been interpreted as part of a putative tumor-enhancing effect of insulin." (PMID 28060743, 2017). "Insulin (either endogenous or exogenous) could well reach concentrations which may contribute to survival of selected malignant tumour cells, especially in insulin-resistant patients." (PMID 28316059, 2017).